SLC6A4 (solute carrier family 6 member 4)
Diseases named in the same sentence as SLC6A4 in open-access papers (continued):
Sharing a sentence is not in itself a finding about the gene and the disease.
schizophrenia (31 papers, 2012 to 2025). A major psychotic disorder characterized by abnormalities in the perception or expression of reality. "For example, SLC6A4 (the serotonin transporter) is involved in the reuptake of serotonin, and its functional polymorphisms have been associated with the incidence of schizophrenia." (PMID 39100210, 2024). "The 5-HTTLPR variant in the promotor area of the serotonin transporter gene SLC6A4 has long been considered a candidate variant for the pathogenesis of schizophrenia for different reasons." (PMID 37109044, 2023). "Here, we aimed to investigate the association of three variable number tandem repeats (VNTR) functional polymorphisms in MAOA and SLC6A4 with schizophrenia in the Iranian population." (PMID 35079035, 2022). "The present study investigated the association of nine polymorphisms in the four 5-hydroxytryptamine receptor (HTR) genes HTR1A, HTR2A, HTR3A, and HTR2C and the gene encoding for the serotonin transporter SLC6A4 with MetS in patients with schizophrenia." (PMID 33807811, 2021). "Regarding the SLC6A4 gene, the homozygous genotype 12R/12R at the STin2 polymorphic locus was repeatedly reported to be linked with a predisposition to schizophrenia development, whereas the 12R/10R heterozygosity appeared to be protective." (PMID 33868590, 2021). "In the present study we found an association between the SLC6A4 rs16965628 polymorphism and attempted suicide among patients with schizophrenia (P-value = 0.00092 and global P-value = 0.01)." (PMID 22594806, 2012). "Seven SLC6A4 single nucleotide polymorphisms (SNPs) were genotyped in 837 schizophrenia patients and 1,473 control individuals." (PMID 22594806, 2012). "Dysfunction or dysregulation of SLC6A4 can lead to alterations in serotonin levels and signaling, which have been implicated in various neuropsychiatric disorders, including depression, anxiety disorders, schizophrenia, and obsessive-compulsive disorder (OCD)." (PMID 39100210, 2024). "This is similar to a prior study which suggested that interaction between variants of 5-HTR2A and SLC6A4 polymorphisms might be involved in the etiology of schizophrenia." (PMID 30483162, 2018). "The objective of this study was to explore the correlation between DRD2, HTR2A, SLC6A4, CYP1A2, and ABCB1 polymorphisms and clozapine response in 100 patients with Treatment-Resistant Schizophrenia." (PMID 38540209, 2024). "The data on possible associations between the SLC6A4 5-HTTLPR variant and schizophrenia are, however, controversial." (PMID 37109044, 2023). "Partial correlation analyses showed significant positive correlations between 5-HTR2A and SLC6A4 mRNA expressions in both schizophrenia patients (r = 0.44, p = 0.004) and controls (r = 0.69, p < 0.001)." (PMID 30483162, 2018). "On the other hand, the antagonists targeting GABRG-3, GABRG-4, DRD5, ADR -A1D/–B2, CHRM-3, and SLC6A4 (all elevated by FD) are under investigation for treating bipolar disorder and schizophrenia." (PMID 24632812, 2014). "In the present study, we wanted to further explore the possible involvement of the serotonin system in suicide among patients with schizophrenia, by analyzing genetic variations in the SLC6A4 gene using a Scandinavian case–control sample." (PMID 22594806, 2012). "We observed an allele association between the SNP rs16965628, located in intron one of SLC6A4, and attempted suicide (adjusted p-value 0.01), among patients with schizophrenia." (PMID 22594806, 2012). "Seven SNPs located in the SLC6A4 gene, were selected and genotyped in 837 patients suffering from schizophrenia and related disorders, of which 738 had information on suicidal behavior, and in 1,473 control individuals." (PMID 22594806, 2012). "Multiple lines of evidence suggest that genetic variation in the serotonin transporter gene (SLC6A4; 5-HTT) is associated with schizophrenia and suicidal behavior." (PMID 22594806, 2012).
schizophrenia (continued). "Structural magnetic resonance imaging (MRI) scans suggested that SLC6A4 might be related to deficits in structural schizophrenia brain networks, indicating that functional genetic research on this polymorphism must be further explored." (PMID 37627285, 2023). "Four candidate genes (DRD2, COMT, 5-HTR2A, and SLC6A4) from dopaminergic and serotoninergic pathways have received the most attention in the literature and have been supposed as the promising candidate genes for schizophrenia and treatment response." (PMID 30483162, 2018). "In summary, dysregulated COMT and SLC6A4 mRNA expressions in schizophrenia provides further evidence supporting that these two genes may implicate in the pathophysiology of schizophrenia." (PMID 30483162, 2018). "In this study, we wanted to elucidate whether SLC6A4 variations is involved in attempted suicide among patients with schizophrenia in a Scandinavian case–control sample." (PMID 22594806, 2012). "The gene SLC6A4 appears to be involved in suicidal ideation among patients with schizophrenia." (PMID 22594806, 2012). "In addition, association studies between genetic variants of the HTR1A, as well as solute carrier family 6, member 4 (SLC6A4) genes and clinical outcomes in schizophrenia, have shown that rs6295 and 5-HTTLPR polymorphisms significantly influence clinical symptoms in schizophrenia." (PMID 36983018, 2023).
bipolar disorder (19 papers, 2004 to 2026). A disorder of the brain that causes unusual shifts in mood, energy, activity levels and the ability to carry out day-to-day tasks. "Age at onset (AAO) of bipolar disorders (BD) could be influenced both by a repeat length polymorphism (5HTTLPR) in the promoter region of the serotonin transporter gene (SLC6A4) and exposure to childhood trauma." (PMID 26542422, 2015). "Ritalin inhibits, amongst other proteins, the same serotonin and dopamine transporters SLC6A4 and SLC6A3 that have been implicated in bipolar disorder." (PMID 25276232, 2014). "Mood stabilizers could also reverse the hypermethylation process of CpG sites of SLC6A4 to be hypomethylated in bipolar disorder." (PMID 28117656, 2016).
pulmonary hypertension (19 papers, 2009 to 2025). Increased pressure within the pulmonary circulation due to lung or heart disorder. "Physiological implication of the SLC6A4 gene in the cardiovascular system includes the proliferation of vascular smooth muscle cell, which is a part of the atherosclerosis process, vasoconstriction of the arterial wall, endothelial damage and pulmonary arterial hypertension." (PMID 40369544, 2025).
irritable bowel syndrome (17 papers, 2011 to 2025). Irritable bowel syndrome (IBS) is a chronic functional condition of the lower gastrointestinal (GI) tract characterized by abdominal pain or discomfort and disordered bowel habit (diarrhea, constipation, or fluctuation between the two). "Association studies of serotonin transporter gene SLC6A4 I/S polymorphism and irritable bowel syndrome (IBS) have shown inconsistent and contradictory results among different populations." (PMID 24069428, 2013).
alcoholism (14 papers, 2011 to 2025). "A similar study on alcoholism in women from 2008 examined the association between SLC6A4 polymorphism and monoamine oxidase A promoter polymorphism (MAOA-VNTR) and severe cases of alcoholism in women." (PMID 40422201, 2025). "A particular strength of our study was also the haplotype-based approach that allowed us to obtain information about common haplotypes within the SLC6A4 gene that have shown a strong association of the SLC6A4 gene variability with alcohol dependence." (PMID 39125658, 2024). "Genes encoding the 5-HTT gene (the serotonin transporter protein; genetic locus SLC6A4) and 5-HT receptor, which may cause different levels of activity of 5-HTT, have been examined as candidate genes for the risk of alcoholism." (PMID 22550993, 2012). "Within the Slc6a4 gene, a repeat element of variable length in the 5′ region and a single nucleotide polymorphism (SNP) in the 3′ untranslated region were shown to influence alcohol dependence and severity of drinking as well as response to 5-HT-targeted therapies in AUD patients, respectively." (PMID 35625928, 2022). "Our preliminary findings shed light on the role of SLC6A4 sequence variations in alcohol dependence, but further investigations are needed to understand the complexity of genetics in AUD." (PMID 39125658, 2024). "In addition, alcohol dependence has been associated with changes in the transcription of the serotonin transporter (5-HTT), which is encoded by the Slc6a4 gene and is responsible for controlling the pattern and magnitude of 5-HT activity." (PMID 35625928, 2022).
mental disorder (14 papers, 2008 to 2023). A disease that has its basis in the disruption of mental process. "The first cluster contained only 3 genes including 5-HTT, SLC6A4, and MAOA, which were associated with 14 mental disorders." (PMID 31626105, 2019). "There is plenty of evidence that the human serotonin transporter (SERT), encoded by asingle gene known as SLC6A4 located on the long arm of chromosome 17, could beinvolved in mental disorders." (PMID 39464543, 2023). "Due to the small sample size, we did not analyze the association of SLC6A4 polymorphism with different mental disorders in three different subtypes of IBS." (PMID 28951738, 2017). "Cluster analysis showed that 5-HTT, SLC6A4, and MAOA are common genetic factors in most mental disorders; the intra-group genes in each cluster were highly correlated." (PMID 31626105, 2019). "Early-life stress may also impact methylation of other genes related to the pathophysiology of various mental disorders, such as BDNF, COMT, MAOA, FKBP5, and SLC6A4." (PMID 33284958, 2021).
obsessive-compulsive disorder (14 papers, 2009 to 2024). A disorder characterized by the presence of persistent and recurrent irrational thoughts (obsessions), resulting in marked anxiety and repetitive excessive behaviors (compulsions) as a way to try to decrease that anxiety. "For example, the serotonin neurotransmitter transporter SLC6A4 is a mouse nonessential gene, and mutations to the human ortholog of this gene cause obsessive-compulsive disorder through a defect in the regulation of serotonin levels." (PMID 26301634, 2015).
Insulin resistance (13 papers, 2012 to 2024). Increased resistance towards insulin, that is, diminished effectiveness of insulin in reducing blood glucose levels. "However, mice with global deletion of Slc6a4 have greater adiposity and insulin resistance than wild-type littermates, in addition to reduced food intake and locomotor activity, probably owing to substantial central effects of SERT deletion." (PMID 37537371, 2023).
post-traumatic stress disorder (13 papers, 2011 to 2025). An anxiety disorder precipitated by an experience of intense fear or horror while exposed to a traumatic (especially life-threatening) event. "Variants of the 5-hydroxy-tryptamine (5HT) transporter gene (SLC6A4) have been studied for their role in the vulnerability to Post-traumatic Stress Disorder (PTSD) among individuals exposed to environmental stress." (PMID 33967853, 2021).
autism spectrum disorder (12 papers, 2010 to 2025). "The low activity allele of the maternal polymorphism, 5HTTLPR, in the serotonin transporter, SLC6A4, coupled with prenatal stress is reported to increase the risk for children to develop autism spectrum disorder (ASD)." (PMID 28821725, 2017). "A point mutation in the SLC6A4 gene was recently identified and shown to be associated with autism spectrum disorders, psychosis, and bipolar patients." (PMID 20942913, 2010). "However, the contribution by SLC6A4 and SLC29A4 mutations in our study remained minor with respect to the whole population of autism spectrum disorders." (PMID 33294225, 2020).
migraine (12 papers, 2013 to 2026). "The relevance of 5-HT in migraine has also been assessed by studying polymorphisms in the gene SLC6A4, coding for the serotonin transporter (SERT), involved in the removal of serotonin from the synaptic cleft back to the presynaptic neuron." (PMID 38397400, 2024). "The STin2 VNTR polymorphism in the gene SLC6A4 encoding the serotonin transporter (SERT) was found to correlate with inconsistent response to triptans in migraine patients." (PMID 35222013, 2021). "Also the genetic variants of the 5-HT transporter gene SLC6A4 are being analyzed in migraine." (PMID 27191890, 2016). "Genetic variants in genes such as SLC6A4 (SERT), DRD2 (dopamine receptor), PRDM16 or CYP1A2, and GNB3 have been associated with a modified therapy outcome with triptans in migraine and cluster headache, respectively." (PMID 35222013, 2021). "A few research groups also correlated the SLC6A4 5-HTTLPR gene with the clinical course of migraine in different populations." (PMID 29922128, 2018). "Polymorphisms in the serotonin transporter gene (SLC6A4) and the hypocretin receptor 1 gene (HCRTR1) may be risk factors for migraine development due to their ability to affect serotonin and hypocretin-1 (HCRT-1) concentrations." (PMID 29922128, 2018).
diabetes (11 papers, 2012 to 2025). "These include CCND2, CILP2, PBX4, SH2B3, SLC6A4, TCF7 and KLF14, which have polymorphisms associated with diabetes risk." (PMID 27029739, 2016).
epilepsy (11 papers, 2013 to 2025). A brain disorder characterized by episodes of abnormally increased neuronal discharge resulting in transient episodes of sensory or motor neurological dysfunction, or psychic dysfunction. "The role of SLC6A4 variants, the gene that encodes the serotonin transporter, has been studied regarding the etiology or neuropsychiatric comorbidities in epilepsy." (PMID 34912196, 2021).
Stroke (11 papers, 2016 to 2025). Sudden impairment of blood flow to a part of the brain due to occlusion or rupture of an artery to the brain. "Several studies have shown that SLC6A4 gene methylation is associated with functional outcome and rehabilitation following stroke." (PMID 40723792, 2025). "Plausible mechanisms for the association between SLC6A4 hypermethylation and poor long-term stroke outcomes is as follows." (PMID 33526821, 2021). "These two risk factors (SI and SLC6A4 hypermethylation) contributed to increase PSD risk which mediate the worse long-term stroke outcomes additively." (PMID 33526821, 2021). "Considering the role of SLC6A4 polymorphisms, two previous studies investigated the association between SLC6A4 polymorphisms and short-term (within 6 months) stroke outcomes." (PMID 33526821, 2021). "The association between the average SLC6A4 methylation value and composite CCVEs was significant, especially in patients with SI at 2 weeks after stroke." (PMID 33526821, 2021). "Studies have found that 2 weeks after stroke, higher SLC6A4 promoter methylation status is independently associated with PSD and is more pronounced 1 year after stroke, and is significantly associated with worsening depressive symptoms within 1 year." (PMID 30728786, 2018). "Recently it has been suggested that serotonin transporter (SLC6A4) and its 5HTTLPR polymorphism could be involved in post stroke recovery." (PMID 33923526, 2021). "The association between SLC6A4 methylation and long-term adverse outcomes may be strengthened in the presence of SI within 2 weeks after stroke." (PMID 33526821, 2021). "Our data suggest that 5-HTTLPR polymorphisms and SLC6A4 promoter methylation may be employed as a non-invasive biological marker of recovery in patients with stroke undergoing rehabilitation." (PMID 33923526, 2021). "After the index stroke, cerebro-cardiovascular events by SLC6A4 methylation status and SI were investigated over an 8–14-year follow-up period and using Cox regression models adjusted for a range of covariates." (PMID 33526821, 2021). "The utility of SLC6A4 hypermethylation for predicting long-term stroke outcomes was superior in patients who experienced SI within 2 weeks of stroke." (PMID 33526821, 2021). "In conclusion, stroke patients with a high SLC6A4 gene methylation value, and/or with SI within 2 weeks after stroke, were more likely to experience composite CCVEs and recurrent stroke." (PMID 33526821, 2021). "Hypermethylation of CpGs 1 and 4, and a high average SLC6A4 methylation value, predicted poor long-term stroke outcomes (composite CCVEs and recurrent stroke), especially in patients who experienced SI within 2 weeks of stroke." (PMID 33526821, 2021). "We investigated the independent and interactive effects of SLC6A4 methylation and SI immediately after stroke on long-term outcomes." (PMID 33526821, 2021). "A higher average SLC6A4 methylation value was a significant predictor of recurrent stroke only in the presence of SI at 2 weeks after stroke, but did not predict any other CCVEs." (PMID 33526821, 2021). "A difference in the latency from the stroke insult could probably play a functional role in modulating the methylation levels of the SLC6A4 promoter." (PMID 33923526, 2021). "In this way, SLC6A4 could be used as non-invasive biomarker in post-stroke patient management, with personalized rehabilitation protocols reducing costs and recovery times." (PMID 33923526, 2021). "So, it is possible to hypothesize that SLC6A4 methylation status and 5-HTTLPR polymorphism could be implicated in post-stroke recovery after rehabilitation treatment." (PMID 33923526, 2021). "Stroke patients with SLC6A4 hypermethylation might have reduced 5-HTT function and 5-HT availability, which would lead to decreased BDNF expression and thus suppress neurogenesis and promote inflammation." (PMID 33526821, 2021).
Stroke (continued). "The principal findings of this study were that both high average SLC6A4 methylation values and SI at 2 weeks predicted worse long-term stroke outcomes, i.e., composite CCVEs and recurrent stroke, at 8–14 years after stroke, independent of covariates." (PMID 33526821, 2021). "SLC6A4 hypermethylation and SI within 2 weeks of stroke both predicted worse long-term outcomes, independent of covariates." (PMID 33526821, 2021). "However, the prognostic roles of SLC6A4 methylation and suicidal ideation (SI) in long-term outcomes of stroke have not been evaluated." (PMID 33526821, 2021). "The effects of methylation of the SLC6A4 gene on stroke outcomes have not been investigated, although hypermethylation of the SLC6A4 gene was related to lower 5-HTT mRNA levels and brain serotonin synthesis." (PMID 33526821, 2021).
type-2 diabetes (9 papers, 2019 to 2024). "A genetic variant of gene encoding SERT (Slc6a4) that reduces its expression, known as the “short” (S) allele, is associated with a higher body mass index (BMI) and the development of type 2 diabetes." (PMID 39199273, 2024).
inflammatory bowel disease (8 papers, 2017 to 2025). A spectrum of small and large bowel inflammatory diseases of unknown etiology. "The serotonin transporter coded by the SLC6A4 gene has been implicated in the pathogenesis of inflammatory bowel disease which includes ulcerative colitis." (PMID 38467948, 2024).
insomnia (8 papers, 2018 to 2025). A sleep disorder characterized by difficulty in falling asleep and/or remaining asleep. "We could predict the role of VVO in modulating the serotonergic synaptic pathway in the treatment of insomnia, and this modulation was associated with MAOB, MAOA, PTGS2, HTR2A, and SLC6A4." (PMID 40004189, 2025). "In summary, our research findings have elucidated that VVO treats insomnia through a variety of components and multiple targets, with MAOB, MAOA, SLC6A4, HTR2A, and others at serotonergic synapses playing a vital role in the process of VVO treating insomnia." (PMID 40004189, 2025). "The results from the PPI analysis show that the targets of VVO for the treatment of insomnia mainly involve MAOB, DRD2, MAOA, IL1B, PTGS2, HTR2A, SLC6A4, and ESR1." (PMID 40004189, 2025).